TMTC4 (transmembrane O-mannosyltransferase targeting cadherins 4)
Description:
Transfers mannosyl residues to the hydroxyl group of serine or threonine residues. The 4 members of the TMTC family are O-mannosyl-transferases dedicated primarily to the cadherin superfamily, each member seems to have a distinct role in decorating the cadherin domains with O-linked mannose glycans at specific regions. Also acts as O-mannosyl-transferase on other proteins such as PDIA3.
Synonyms: FLJ14624; FLJ22153; DFNB122
Tractability: Antibody: UniProt predicts a signal peptide or a membrane-spanning region. PROTAC: its protein half-life has been measured.
Gene: Protein-coding gene on chromosome 13 (100,603,625 to 100,675,633, reverse strand). Ensembl gene ENSG00000125247.
Subcellular location: Membrane; Endoplasmic reticulum
Subcellular location (Human Protein Atlas): Vesicles
Gene Ontology:
Molecular function: ATPase binding; dolichyl-phosphate-mannose-protein mannosyltransferase activity; protein binding; mannosyltransferase activity
Biological process: protein O-linked glycosylation via mannose; endoplasmic reticulum unfolded protein response
Cellular component: endoplasmic reticulum; membrane
Genetic constraint (gnomAD): Loss-of-function variants: 59 observed, 86.59 expected, observed/expected ratio (o/e) 0.68, 90% interval 0.55 to 0.85. The upper end of that interval is the gene's LOEUF score, 0.85, which puts it in group 3 of 6, group 1 being the genes least tolerant of losing a copy. Missense variants: 864 observed, 989.29 expected, observed/expected ratio (o/e) 0.87, 90% interval 0.82 to 0.92. Synonymous variants: 379 observed, 402.83 expected, observed/expected ratio (o/e) 0.94, 90% interval 0.86 to 1.02.
Homologues: Orthologues: chimpanzee TMTC4 (99% identical), macaque TMTC4 (95% identical), dog TMTC4 (90% identical), pig TMTC4 (90% identical), rat Tmtc4 (89% identical), rabbit TMTC4 (89% identical), guinea pig TMTC4 (89% identical), mouse Tmtc4 (88% identical), tropical clawed frog tmtc4 (73% identical), zebrafish tmtc4 (66% identical), Caenorhabditis elegans F38B6.6 (34% identical). Paralogues in human: TMTC1 (33% identical), TMTC2 (33% identical), TMTC3 (33% identical), TTC7B (13% identical), IFT88 (12% identical), TTC7A (12% identical), CFAP70 (11% identical), TTC6 (11% identical), TTC34 (10% identical), OGT (9% identical), TTC16 (9% identical), TTC13 (9% identical), and 2 more.
Diseases named in the same sentence as TMTC4 in open-access papers:
TMTC4 is named in the same sentence as 13 diseases in open-access papers, as found by Europe PMC text mining. Sharing a sentence is not in itself a finding about the gene and the disease. The quoted sentences say what the papers report.
hearing loss (3 papers, 2023 to 2025). "Similar to the cells from patients with hearing loss and TMTC4 missense variants, TMTC4 p.E183K and p.A192V HEK cells were found to have an elevated ratio of CHOP/S-XBP1 mRNA at baseline (P < 0.001)." (PMID 37943620, 2023). "Small-molecule inhibition of the PERK arm of the UPR and integrated stress response (ISR) using integrated stress response inhibitor (ISRIB) protected hair cells and attenuated hearing loss in the Tmtc4–/– mouse as well as in a rodent model of noise-induced hearing loss." (PMID 39570676, 2025). "Human hearing loss is associated with autosomal recessive TMTC4 variants." (PMID 37943620, 2023). "Furthermore, we identified a human family in which Tmtc4 variants segregate with adult-onset progressive hearing loss." (PMID 37943620, 2023). "Our group implicated the UPR and ER stress in rapidly progressive genetic hearing loss due to absence of the novel deafness gene, TMTC4, as well as in noise induced hearing loss (NIHL) and cochlear synaptopathy." (PMID 39333235, 2024). "Furthermore, though other Tmtc family members, including TMTC2, have been implicated in hearing loss, there have previously not been any humans described with TMTC4-associated hearing loss." (PMID 37943620, 2023).
deafness (2 papers, 2020 to 2023). An inherited or acquired condition characterized by the complete loss of the ability to hear from one or both ears. "We recently demonstrated that transmembrane and tetratricopeptide repeat 4 (Tmtc4) is a recently described deafness gene in mice." (PMID 37943620, 2023). "We created a hair cell–specific conditional KO mouse that phenocopies the constitutive KO with postnatal onset deafness, demonstrating that Tmtc4 is a hair cell–specific deafness gene." (PMID 37943620, 2023). "Homozygous cKO mice (Myo15Cre/Tmtc4fl/fl) exhibited normal ABRs and DPOAEs at auditory onset (P13) and rapid progression to complete deafness by P26, similar to constitutive Tmtc4-KO mice." (PMID 37943620, 2023). "Transmembrane and tetratricopeptide repeat 4 (Tmtc4) is a deafness gene in mice." (PMID 37943620, 2023). "Mice lacking Tmtc4 have normal postnatal onset of hearing, measured by auditory brainstem response (ABR) thresholds, at P13, with rapid progression to complete deafness by P26, accompanied by subsequent loss of sensory hair cells in the cochlea." (PMID 37943620, 2023).
prostate carcinoma (2 papers, 2021 to 2022). A carcinoma that arises from epithelial cells of the prostate gland. "TMTC4 was higher expression in LGG, glioblastoma (GBM), bile duct cancer (CHOL), COAD, large B‐cell lymphoma (DLBC), prostate cancer (PRAD), rectal cancer (READ), and THYM than in normal tissue." (PMID 34894053, 2022).
colon cancer (1 paper, 2024). "CD has no common overregulated genes with gastric cancer and one gene (TMTC4) and one TF (ZNF3) with colon cancer, located in the endoplasmic reticulum and membrane." (PMID 39791702, 2024).
genetic disorder (1 paper, 2014). "Although TMTC4 has not previously been associated with any genetic disorder, we are now evaluating it as the possible cause of this condition." (PMID 24375697, 2014).
tumor (1 paper, 2021). "This may be an explanation for the TMTC4 overexpression in tumor cells." (PMID 33925440, 2021).
TMTC4 also shares sentences with these, for which no sentence is quoted: bile duct cancer (1 paper); diabetes (1); gastric cancer (1); glioblastoma (1); infection (1); progressive sensorineural hearing loss (1); rectal cancer (1).